RYK (receptor like tyrosine kinase)
Diseases named in the same sentence as RYK in open-access papers (continued):
Sharing a sentence is not in itself a finding about the gene and the disease.
tumor (14 papers, 2013 to 2024). "sGAG‐mimetic alginate sulfate leads to activation of a specific set of RTKs (FGFR3 and RYK) in tumor cells and the downstream FAK‐PI3K signaling axis." (PMID 39083319, 2024). "After performing multivariate analyses, neoplasm histologic grade (G3 vs. G2, HR = 3.72; 95% CI, 2.02–6.83, p < 0.001) and RYK expression status (high vs. low, HR = 0.44; 95% CI, 0.22–0.91, p = 0.027) were significant risk factors for OS in this patient group." (PMID 37242509, 2023). "The expression of COPB2, DCTN4, RYK, TARS, and UIMC1 indicated association with the change of fraction of immune cells in LSCC patients; two genes, COPB2 and RYK, indicated different expression in various tumor stages of LSCC." (PMID 35715770, 2022). "Researchers found that silencing of the WNT-5A receptors Frizzled 8 (FZD8) and RYK attenuated TGF-β-induced ECM expression; future work needs to be done to analyze the expression status of RYK in different tumor stages and its role in progression of LSCC." (PMID 35715770, 2022). "The results of immunohistochemistry analysis showed that COPB2 and RYK appeared brownish-yellow in tumor tissues of advanced LSCC patients." (PMID 35715770, 2022). "Subcutaneous injection of GC cells with stable RYK knockdown into mice showed reduced tumor growth, and increased survival compared to RYK-proficient control mice." (PMID 32486243, 2020). "In line with the cDNA array, the TMA also revealed that FZD5 and RYK expression levels were significantly higher in malignant tissues compared to adjacent tumor-free tissues of the same patients and also compared to BPH patients (data not shown)." (PMID 29930766, 2018). "In contrast to this, RYK ICD staining, was significantly lower in tumor compared to tumor-free tissue (p<0.001) and RYK ICD expression was also lower in tumor tissue vs. BPH patients (data not shown)." (PMID 29930766, 2018). "Finally, RYK appeared high-expression in tumor tissues of advanced LSCC patients based on immunohistochemistry staining." (PMID 35715770, 2022). "Through a siRNA library screening that targeted most genes encoding RTKs and subsequent validation, we found that knockdown of 4 RTK receptors (FGFR2, RON, EPHA1, and RYK) via siRNA sensitized MET-addicted tumor cells to PF, while b-FGF-induced activation of FGFR2 conferred resistance to the PF." (PMID 26528757, 2015). "Finally, COPB2 and RYK showed high-expression in tumor tissues of advanced LSCC patients." (PMID 35715770, 2022). "We found increased expression of FZD6, FZD7, RYK, and PTK7 in tumors, as well as a highly significant increase in FZD7 in tumor-adjacent cells." (PMID 31261741, 2019). "Analysis of the staining patterns of the receptors in tumor tissue showed a positive correlation between FZD5 and RYK expression (r=0.4404, p<0.001)." (PMID 29930766, 2018). "In conclusion, two genes, COPB2 and RYK were found to be significantly correlated with tumor stages of LSCC and represented negative correlation with overall survival of LSCC patients." (PMID 35715770, 2022).
hematological cancers (1 paper, 2023). "Additionally, with the inhibition of RYK with anti-RYK antibodies in mice with hematological cancers, the mice were sensitized to fluorouracil (5-FU) treatment." (PMID 37242509, 2023).
RYK also shares sentences with these, for which no sentence is quoted: acute lymphoblastic leukemia (2 papers); acute myeloid leukemia (1); craniofacial clefts (1); diffuse malignant peritoneal mesothelioma (1); Hematological Disease (1); larynx squamous cell carcinoma (1); metastatic cancer (1).